APOE (apolipoprotein E)
Diseases named in the same sentence as APOE in open-access papers (continued):
Sharing a sentence is not in itself a finding about the gene and the disease.
atherosclerosis (continued). "Acknowledging the prominent underlying role of inflammation in the initiation and progression of vascular disease, and the numerous anti-inflammatory roles ascribed to Tβ4, we characterised the inflammatory responses of Tβ4-/Y; ApoE-/- and Tβ4+/Y; ApoE-/- mice during atherosclerosis." (PMID 37724952, 2023). "The apoE−/− mice represent a recognized model for studying the mechanisms of atherosclerosis." (PMID 35906520, 2023). "APOE-ε4 allele[s] is a risk factor for Alzheimer's disease (AD) and Amyloid-Related Imaging Abnormalities (ARIA) in anti-amyloid beta therapy, and is also associated with cerebrovascular risk factors such as hyperlipidemia or atherosclerosis." (PMID 39081988, 2023). "In this study, we investigated the therapeutic effects of the sGC stimulator BAY 41-2272 (Bay 41) and the sGC activator BAY 60-2770 (Bay 60) on endpoints of atherosclerosis and renal disease as well as inflammation and oxidative stress in diabetic Apolipoprotein E knockout (ApoE-/-) mice." (PMID 37502180, 2023). "In addition, protocatechuic acid has been shown to mitigate monocyte adhesion and blunt atherosclerosis in ApoE-/- mice." (PMID 37108307, 2023). "Evidence from experimental studies showed that carnosine administration lowered TG levels and prevented LDL-C oxidation and created stable covalent conjugates with the aldehydes produced during LDL-C oxidation in diabetic apolipoprotein E (−/−) mice, inhibiting the progression of atherosclerosis." (PMID 38004228, 2023). "Standard in-bred strains of mice are highly resistant to the development of atherosclerosis; therefore, genetic modification of their lipid metabolism is required (i.e., through deletion of ApoE or LDL-R genes)." (PMID 38164438, 2023). "One study which involved double knockout of ApoE and mitochondrial DNA polymerase G (POLG) showed an accumulation of mtDNA damage in circulating cells and vessel walls, promoting atherosclerosis as well as being associated with the formation of vulnerable plaques." (PMID 37507899, 2023). "However, our later study showed that systemic Nampt overexpression aggravated atherosclerosis development in apolipoprotein E knockout (ApoE-/-) mice." (PMID 36831235, 2023). "Raman signal assignments of atherosclerosis of ApoE KO mice." (PMID 37476064, 2023). "Macrophages contribute very importantly to lesion progression, in ApoE−/− mice, the number of macrophages in early atherosclerosis is determined by recruitment; in more advanced lesions, however, it was largely dependent on proliferation of local macrophages, rather than monocyte." (PMID 36823573, 2023). "ApoE−/− mice of C57BL/6 background develop atherosclerosis throughout the arterial tree, including the aortic root at the base of the valve, and these lesions, a condition that favors vascular inflammation, are accelerated when mice are fed with a Western diet." (PMID 37762794, 2023). "STAT3 phosphorylation was previously identified as a major inducer of the inflammation-resolving M2 phenotype in macrophages by increasing IL-10 expression and was suggested as a potential mechanism for the protection of ApoE LysMPTP1B(−/−) mice against atherosclerosis." (PMID 37828508, 2023). "SAA is also significantly elevated in obese apoE−/− mice with accelerated atherosclerosis." (PMID 37004910, 2023). "Therefore, we generated ApoE−/−NPRC−/− double knockout mice to establish a combined model of atherosclerosis and NPRC deletion, and littermate ApoE−/− mice served as a control model of atherosclerosis." (PMID 37553374, 2023). "ApoE−/− mice fed a high-fat diet were used to establish an atherosclerosis model." (PMID 37990246, 2023). "Furthermore, the function of each isoform differs in different organs; notably, skeletal muscle-specific FOXO1 overexpression in ApoE−/− mice suppresses atherosclerosis." (PMID 37520709, 2023).
atherosclerosis (continued). "The effect of UAMC-3203 (12.35 mg/kg/day) on atherosclerosis was evaluated in ApoE−/−Fbn1C1039G+/− mice fed a western-type diet (WD) for 12 weeks (n = 13 mice/group) or 20 weeks (n = 16–21 mice/group) to distinguish between plaques without and with established IP angiogenesis, respectively." (PMID 37120604, 2023). "One study found that atherosclerosis-prone apolipoprotein E-deficient (ApoE−/−) mice induced atherosclerosis in the presence or absence of a commonly used ferroptosis inhibitor fer-1." (PMID 36831172, 2023). "In this study, we provided more reliable evidence for the anti-atherosclerotic effects of adropin by using ApoE-/-/Enho-/- mice, and further demonstrated that adropin inhibited the occurrence and development of atherosclerosis in high-fat diet (HFD)-fed ApoE-/- mice by inhibiting the EndMT." (PMID 37903785, 2023). "Interestingly, fisetin has a clear inhibitory effect on arginase, and also ameliorates atherosclerosis by regulating PCSK9 and LOX-1 in apolipoprotein E deficient mice." (PMID 37047807, 2023). "This study establishes the apoE−/− rat as suitable model for atherosclerosis imaging." (PMID 38079017, 2023). "Additionally, miR-let7 has been shown to attenuate the progression of atherosclerosis in ApoE−/− mice and facilitate M2 macrophage infiltration and polarization." (PMID 37259293, 2023). "A constitutive suppression of miR-145 by ASO exacerbated monocyte infiltration in the liver, while systematic overexpression of miR-145 by lentivirus alleviated obesity, inflammation, and insulin resistance in db/db mice, and moderated atherosclerosis in ApoE−/− mice." (PMID 39872853, 2023). "MiD49/51 expression was increased in the aortic valve endothelial cells (ECs) of high-fat diet-induced atherosclerosis in ApoE-/-mice and IL-8-induced human umbilical vein endothelial cells (HUVECs), which accelerated dynamin-related protein 1 (Drp1)-mediated mitochondrial fission." (PMID 38203413, 2023). "Moreover, chronic uremia promoted atherosclerosis in uremic apoE−/− mice by promoting endoplasmic reticulum (ER) stress-related inflammation, including activating ER stress induced inflammation via activating IKK phosphorylation." (PMID 36823573, 2023). "To explore accessorily whether MC4R deficiency promotes atherosclerosis, we crossed MC4RTB/TB mice with apolipoprotein E (ApoE) knockout (ApoE−/−) mice to generate double-deficient MC4R and ApoE (ApoE−/−;MC4RTB/TB) mice." (PMID 37957201, 2023). "We demonstrated that oridonin alleviated atherosclerosis in ApoE−/− mice." (PMID 37155118, 2023). "Herein, we aimed to explore whether highland barley supplementation can prevent atherosclerosis progression and improve gut microbiota disorder in apolipoprotein E knockout (ApoE−/−) mice." (PMID 37836470, 2023). "When HDAC3 is knocked down, ApoE−/− mice develop atherosclerosis, and their vessel ruptures." (PMID 38031118, 2023). "Infusions of such M2‐exosomes into ApoE‐/‐ mice reduced western diet‐induced haematopoiesis in the bone marrow and the spleen, as well as inflammatory activity in monocytes and macrophages that led to the resolution of atherosclerosis." (PMID 36775986, 2023). "Finally, we aimed at introducing a protective genotype into the apolipoprotein E (APOE) transcript, introducing the rs7412 SNP (R158C), which could transfer the neutral ε3 allel (ca. 78% caucasian carriers) into the protective ε2 allel, which was shown to largely reduce the risk for atherosclerosis." (PMID 37462074, 2023). "Similarly, exosomes produced by bone marrow-derived macrophages (BMDMs) under hyperglycemic conditions exhibit high miR-486-5p levels, and when infused in high-fat cholesterol diet-fed ApoE−/− mice, increase myelopoiesis and atherosclerosis progression." (PMID 37849988, 2023). "Moreover, the anti-atherosclerosis effect of Icariin was also observed in ApoE-/- mice, rats, and rabbit models." (PMID 36984421, 2023).
atherosclerosis (continued). "However, GEO and citral exhibited a favorable effect and improved general gut microbiota composition, indicating that GEO and citral treatment restored gut microbiota and ameliorated atherosclerosis in GC ApoE−/− mouse model." (PMID 37210385, 2023). "In the diabetic apolipoprotein E-deficient mouse model, decreased levels or lack of GPx-1 accelerate diabetes-associated atherosclerosis." (PMID 37107209, 2023). "We found that the deficiency in caspase-1 in Tg26+/−/ApoE−/−/Casp-1−/− mice resulted in significantly fewer atherosclerosis plaques in the thoracic aorta, but not in the entire aorta including the arch, thoracic, and abdominal aorta, nor in the aortic root." (PMID 37629052, 2023). "Therefore, suggesting that GDF15 prevents atherosclerosis in the ApoE knockout mice, which is nowadays the most used murine model for atherosclerosis because of its displayed hypercholesterolemic status." (PMID 36992609, 2023). "Additionally, we have found that overexpression of systemic Nampt aggravates atherosclerosis in ApoE-/- mice, and others have demonstrated that inhibition of Nampt reduces atherosclerosis." (PMID 36831235, 2023). "Also, in a model of atherosclerosis using mice ApoE-KO or double KO also for Mas, it was found that Ang 1-7 mediated endothelial-dependent vasorelaxation specifically through the Mas receptor." (PMID 37959338, 2023). "Given serum cholesterol levels were unchanged in the ApoE−/− mice, we hypothesized that PF-06409577 may reduce atherosclerosis by activating AMPKβ1 complexes within immune cells, including macrophages." (PMID 38026185, 2023). "Similarly, inhibition of DRP1, a mitochondrial fission regulator, decreased endothelial impairment and atherosclerosis progression in apolipoprotein E (ApoE) knock-out mice, as well as VSMCs calcification." (PMID 38020895, 2023). "The adeno-associated viral (AAV) vectors expressing HO-2 was constructed, and the mice were received saline (ApoE−/−), AAV (ApoE−/−), AAV–HO–2 (ApoE−/−) on WD at 12 weeks and their plasma lipids, inflammatory cytokines, atherosclerosis were evaluated for 16 weeks." (PMID 36593926, 2023). "In addition, the global deletion of FAPα in apolipoprotein E (ApoE) knockout mice has been shown to accelerate the progression of atherosclerosis." (PMID 38136590, 2023). "Here, we showed that oridonin attenuated atherosclerosis in hyperlipidemic ApoE knockout mice." (PMID 37905351, 2023). "The majority of experimental atherosclerosis studies evaluating the impact of SGLT2 inhibitors have been performed in apolipoprotein E deficient mice with and without diabetes mellitus." (PMID 37111578, 2023). "In order to further study the role of CHH in the development of atherosclerosis, we conducted this study: ApoE-/- mice were fed a high-cholesterol diet for 8 weeks to promote the formation of atherosclerotic plaques and then exposed to a control environment or CHH for 4 weeks." (PMID 37324194, 2023). "A possibility of evaluating the involvement of Gpr15 in the pathogenesis of MI, a combination of an atherosclerosis mouse model (e.g., apolipoprotein E knockout mice) and Gpr15 knockout mouse model might be suitable." (PMID 36613626, 2022). "The ApoE model could be exacerbated with high fat diet induction model for acceleration of atherosclerosis and NAFLD." (PMID 35172845, 2022). "P210-PAM immunization reduced atherosclerosis in ApoE–/– mice." (PMID 35536648, 2022). "Furthermore, the ApoE knockout mouse model has been widely applied to mechanistic and therapeutic research on atherosclerosis." (PMID 35172845, 2022).
atherosclerosis (continued). "Also, in hypertensive atherosclerosis-prone mice (BPH/ApoE − / −), sympathetic activation accelerates the progression of atherosclerosis." (PMID 35235172, 2022). "In other words, the migration and adhesion of monocytes, the activation of macrophages, cholesterol metabolism, and the contraction and morphological transformation of smooth muscle cells are closely related to the onset and progression of atherosclerosis in ApoE KO mice." (PMID 36286293, 2022). "APOE was reported to attenuate unresolvable inflammation as a checkpoint by complex formation with activated C1q in the complement activation pathway and subsequently reducing C5 and the inflammatory burden in atherosclerosis and Alzheimer disease." (PMID 35379280, 2022). "To explore the role of betaine in SAH metabolism and atherosclerosis, we constructed an ApoE−/− mouse model along with the heterozygous SAHH gene knockout (SAHH+/−), and then observed the effect of dietary betaine supplementation in SAHH-deficient ApoE−/− mice." (PMID 35277077, 2022). "Unexpectedly, ABCC10 deficiency does not affect triglyceride levels or atherosclerosis in ApoE-deficient mice." (PMID 36430292, 2022). "It was reported that transgenic introduction of human sclerostin could inhibit inflammatory cytokines and chemokines, while prevent AA and atherosclerosis progression in ApoE-/- mice with angiotensin II (AngII) infusion." (PMID 35966595, 2022). "The Apolipoprotein E knock-out (ApoE–/–) mouse model is widely used to study atherosclerosis." (PMID 36507350, 2022). "In addition, LDL receptor or apoE knockout (KO) mice overexpressing LPL showed protection against atherosclerosis." (PMID 35456470, 2022). "Atherosclerosis lesions were aggravated by ox‐LDL‐M‐EVs carrying miR‐19b‐3p in ApoE−/− mice." (PMID 34910364, 2022). "In this study, L. plantarum ZDY04 could significantly inhibit the development of TMAO-induced atherosclerosis in ApoE−/− mice as compared with the control." (PMID 36159325, 2022). "Previously work has shown that treatment of ApoE−/− mice with IgG from an atherosclerotic animal promotes atherosclerosis development and prevention of proper germinal center formation or function, either by blocking AID or CD40 signaling, has an atheroprotective effect." (PMID 36461105, 2022). "Transgenic introduction of human sclerostin in ApoE-/- mice could suppress AA and atherosclerosis progression." (PMID 35966595, 2022). "Of note, in ApoE−/− mice, knockdown of Nrf2 has a protective effect against atherosclerosis." (PMID 36231004, 2022). "Additionally, pharmacological inhibition of TLR9 can attenuate the e-cigarettes exacerbated atherosclerosis in ApoE KO mice." (PMID 35463745, 2022). "Genetically modified mice revealed the protective role of AKT1 in vascular function, with AKT1 KO mice on an ApoE−/− background displaying severe peripheral vascular disease, atherosclerosis, occlusive coronary artery disease, plaque vulnerability, and cardiac dysfunction." (PMID 35990823, 2022). "Macrophages overexpressing 12/15-lipoxygenase (12/15-LO) show increased levels of lipoxin A4, which downregulates several proinflammatory cytokines, resulting in atheroprotection in ApoE−/− mice overexpressing 12/15-LO in macrophages and increased atherosclerosis in ApoE−/− 12/15-LO−/− mice." (PMID 34876704, 2022). "ApoE-KO mice fed with Western diet and treated with acacetin showed protection against atherosclerosis through NRF2 pathway, which increased reductase levels in circulation and aortic roots, decreased plasma inflammatory factor levels, as well as accelerated lipid metabolism." (PMID 35204118, 2022). "Moreover, DF-induced arterial wall thickening and atherosclerosis in the ligated LCA were significantly reduced in CDH5-Cas9/sgRNA-Txndc5 nanoparticle–treated ApoE−/− mice, compared to those receiving control nanoparticles." (PMID 35061532, 2022).
atherosclerosis (continued). "In addition, a recent study indicated that DHM significantly suppressed foam cell formation by regulating cholesterol efflux in macrophages, thereby protecting ApoE−/− mice from atherosclerosis." (PMID 36003494, 2022). "Simultaneously, iron intake restriction or iron chelation therapy could suppress iron-aggravated atherosclerosis in ApoE-/- FPNwt/C326S mice." (PMID 35450412, 2022). "In addition, a TRPM2 antagonist N-(p-amylcinnamoyl) anthranilic acid (ACA) was able to inhibit atherosclerotic development in an ApoE−/− mouse model of atherosclerosis." (PMID 35563730, 2022). "We established a mouse model of atherosclerosis by feeding ApoE-/- mice a high-fat diet." (PMID 36006939, 2022). "However, the apoE−/− mice that benefited from a high-fat diet resulted in accelerated atherosclerosis progression." (PMID 36012362, 2022). "H&E staining of aortic sinus sections from the WT CD, ApoE CD, ApoE WD, and ApoE WD EX groups was used to visualize the pathological syndromes of atherosclerosis as representative photomicrographs; we quantified these images to determine vascular thickness and plaque area." (PMID 35256637, 2022). "In addition, we found that binding stimulation made symptoms of atherosclerosis more severe in ApoE−/− mice." (PMID 35558553, 2022). "Knocking down METTL14 could inhibit the development of atherosclerosis in high-fat diet-treated APOE−/− mice." (PMID 35543357, 2022). "Thus, we conclude that DHC ameliorates atherosclerosis in ApoE−/− mice by inhibiting inflammation, likely by targeting macrophage p65- and ERK1/2-mediated pathways." (PMID 34552216, 2022). "To determine whether the administration of recombinant IL-27 affects the initiation of atherosclerosis, we treated 6-week-old ApoE−/− mice with IL-27/anti-IL-27p28-Ab/PBS while they were fed a high-fat diet for 8 weeks." (PMID 36405994, 2022). "Furthermore, sphingolipid inhibitor d-PDMP (d-threo-1-phenyl-2-decanoylamino-3-morpholino-1-propanol, a glycosphingolipid inhibitor), has been reported to reduce lipid uptake and vascular inflammation and to protect against atherosclerosis in ApoE−/− mice." (PMID 36361754, 2022). "In atherosclerosis, which shares similar pathological features with CAVD, DHM has been shown to increase endothelial nitric oxide production in apolipoprotein E-deficient mice (ApoE−/−) and protect human umbilical vein endothelial cells from oxidative damage." (PMID 36003494, 2022). "Similarly, acacetin exerts antioxidant potential against atherosclerosis through Nrf2 pathway in apoE−/− mice." (PMID 36590896, 2022). "Furthermore, Apc001PE showed no influence on the suppressive effect of sclerostin on inflammatory cytokines and chemokines expression, AA and atherosclerosis progression in hSOSTki.Col1a2+/G610C.ApoE-/- mice with AngII infusion." (PMID 35966595, 2022). "Antibodies-mediated depletion of NK cells in ApoE−/− mice greatly attenuated atherosclerosis." (PMID 34980160, 2022). "In addition, several knockout (KO) rabbits have been established recently and applied for the study of atherosclerosis, including apoE, LDL receptor and cholesteryl ester transfer protein." (PMID 35712258, 2022). "Notably, these experiments revealed that dietary low iron alleviates atherosclerosis in ApoE KO mice by down-regulating proteins involved in aortic inflammation, vascular remodeling, and focal adhesion." (PMID 36555552, 2022). "Another study on CD11d and APOE knockout mice revealed that CD11d has a proatherogenic role because the absence of CD11d has reduced the formation foam cells, proinflamatory cytokines which are the key steps in atherosclerosis." (PMID 35241081, 2022). "The ability of apoE to inhibit smooth muscle cell migration and proliferation may account for its ability to not only suppress hypercholesterolemia-induced atherosclerosis but also to inhibit endothelial denudation-induced neointimal hyperplasia." (PMID 36077289, 2022).